ABCG2 (ATP binding cassette subfamily G member 2 (JR blood group))
Diseases named in the same sentence as ABCG2 in open-access papers (continued):
Sharing a sentence is not in itself a finding about the gene and the disease.
gout (continued). "ABCG2 rs2231142 demonstrated a strong association with HUA, and highlighted the role of rs2231142 in the pathogenesis of reduced cellular urate efflux, HUA, and early-onset gout." (PMID 34834509, 2021). "The estradiol levels of hyperuricemia/gout patients and healthy controls were compared, and a hyperuricemia mouse model was used to observe the urate-lowering effect of estradiol and the changes in ABCG2 expression in the kidney and intestine." (PMID 34144706, 2021). "Further sequencing analyses revealed that neither of these ABCG2 mutations was detected in a previously enrolled cohort of 360 patients with hyperuricemia/gout and a cohort of 132 normouricemia control subjects of European descendent." (PMID 33669292, 2021). "Since ABCG2 plays a pivotal role in uric acid clearance, its malfunction may lead to hyperuricemia and gout." (PMID 33801813, 2021). "It should be noted that there is a subset of other function-impairing SNPs in ABCG2, but most of them have not yet been associated with pediatric hyperuricemia or early-onset gout." (PMID 34206432, 2021). "However, even though it has been shown that estrogen can regulate the expression of ABCG2 and serum urate, direct administration of estrogen to male gout patients is inappropriate." (PMID 34144706, 2021). "The reduced uric acid excretion by ABCG2 in the intestine leads to hyperuricemia and gout." (PMID 31254042, 2020). "Previous studies have reported rs2231142 (Q141K) in ABCG2 as a genetic factor in early-onset gout." (PMID 32090094, 2020). "While the role of genetic variants of ABCG2 and SLC22A12 in the gout pathogenesis has been reported, substantial inconsistencies and certain discrepancies in multiple populations of European and Asian ancestries exist due to the effect of various genes and different genetic backgrounds." (PMID 30621105, 2019). "Therefore, it is necessary to replicate this investigation to other populations and on larger cohorts, to verify the influence of ABCG2 SNP as a risky factor in prognosis of gout renal comorbidities." (PMID 31367212, 2019). "On the other hand, the 19 rare non-synonymous variants of ABCG2 identified in Japanese gout cohort were not shared among the population samples that were tested in Czech gout cohort where eight rare non-synonymous ABCG2 variants were identified." (PMID 30894219, 2019). "The contribution of ABCG2 variants in predicting primary hyperuricemia/gout seems to be limited mainly to the absence of a functional characterization of rare variants." (PMID 30894219, 2019). "Among these, ABCG2 and SLC22A12 genes are known risk factors for gout in different populations." (PMID 30621105, 2019). "Besides leading to hyperuricemia, ABCG2 dysfunction was also found to be involved in subsequent steps in gout formation." (PMID 30899057, 2019). "In our previous study, we analyzed the ABCG2 gene in a cohort of 145 subjects with gout." (PMID 30894219, 2019). "While several studies have reported the relationship between ABCG2 and SLC22A12 variants and gout in various ethnic populations, to our best knowledge, the current study was the first one to investigate the genotype distributions and effects of these SNPs on the Vietnamese population." (PMID 30621105, 2019). "In addition to previous reports in different populations, our results provide more evidence on the association of ABCG2 rs72552713 and SLC22A12 rs11231825 with gout and serum uric acid in the Vietnamese population." (PMID 30621105, 2019).
gout (continued). "In our previous study employing genetic analyses for gout patients in Japan and functional analyses of some non-synonymous rare variants of ABCG2, we found that multiple rare and common variants of ABCG2 are independently associated with gout risk." (PMID 31003562, 2019). "Additionally, we found that ABCG2 rs12505410 had signification differences of genotypes in serum uric acid levels and systolic blood pressure among gout patients." (PMID 30621105, 2019). "Mutations in these UA transporters (ABCG2, SLC22A12, NPT1) also leads to hyperuricemia and gout." (PMID 29850377, 2018). "Later it was confirmed that ABCG2 dysfunction in renal tubules may lead to early onset gout which has a familial background." (PMID 29850377, 2018). "In addition, we examined the effect of uric acid, an ABCG2 substrate related to gout development, on the ABCG2-ATPase activity in isolated insect cell membranes." (PMID 29749379, 2018). "In conclusion, based upon GWAS of gout and hyperuricemia simultaneously, we revealed that ABCG2 gene contributed to the development of not only hyperuricemia but also gout, affecting the IL-8 release from EC to cause dysregulation of inflammation and the development of gouty attack." (PMID 29453348, 2018). "Variation in ABCG2 function may play a role in the development of tophaceous disease in some populations with high prevalence of severe gout." (PMID 28270222, 2017). "For all definitions tested, ABCG2 and SLC2A9 were associated with gout at genome-wide significance." (PMID 28793914, 2017). "All the urate transporter-coding genes, ABCG2, SLC2A9, SLC17A1 and SLC17A4, showed association with both the serum urate concentration and progression from hyperuricemia to gout and could affect the risk of gout." (PMID 28252667, 2017). "This study provides evidence that variation in ABCG2 function may play a role in the development of tophaceous disease in some populations with high prevalence of severe gout." (PMID 28270222, 2017). "Our study provides an improved understanding of ABCG2 variations in patients with gout and, as shown by haplotype analysis, that ABCG2 may have a role in gout susceptibility." (PMID 28855613, 2017). "In the Aotearoa New Zealand study, population-specific effects were observed, with several ABCG2 SNPs (rs2231142 (Q141K) and rs10011796) associated with tophi in Western Polynesian people with gout, independent of highest recorded urate and disease duration." (PMID 28566086, 2017). "For example, ABCG2 was identified as a renal proximal tubular urate efflux transporter when a GWAS showed that SNPs in ABCG2 were correlated with altered serum urate levels and gout." (PMID 25797421, 2015). "Patients with mild to severe ABCG2 dysfunction accounted for 78.4% of gout cases." (PMID 24857923, 2014). "Furthermore, the SNPs Q141K and Q126X in the human ABCG2 gene have recently been recognized as clinical biomarkers to assess hyperuricemia and gout." (PMID 24857923, 2014). "Our data provide further support for the concept that the ABCG2 141 K allele does not increase hyperuricemia/gout risk through direct effects on renal tubular uric acid transport." (PMID 24476385, 2014). "The association between these three common ABCG2 single-nucleotide polymorphisms (SNPs) and gout has not been thoroughly characterized in the Han Chinese male population." (PMID 24857923, 2014). "Previous studies identified several transporter genes associated with gout, such as ATP-binding cassette transporter, subfamily G, member 2 (ABCG2/BCRP), GLUT9/SLC2A9, monocarboxylate transporter 9 (MCT9/SLC16A9), and organic anion transporter 4 (OAT4/SLC22A11)." (PMID 24318514, 2014). "These include ABCA1 (HDL-deficiency, Tangier disease), ABCB4 (progressive familial intrahepatic cholestasis type 3; PFIC3), ABCB11 (PFIC2), ABCC2 (Dubin-Johnson syndrome), ABCC6 (pseudoxanthoma elasticum, general arterial calcification of infancy) and ABCG2 (gout)." (PMID 24316454, 2014).
gout (continued). "Furthermore, we had indication for gender interaction, as separate analyses in females and males revealed association with gout for both SLC2A9 SNPs, whereas ABCG2 SNP rs2231142 only showed significant association in males, but not in females." (PMID 19890391, 2009). "In addition, we found a significant association between the exonic SNP rs2231142 in ABCG2 and gout, again supporting the results of a prior GWA on serum UA levels and gout." (PMID 19890391, 2009). "Similarly, the two non-functional ABCG2 variants in a Han Chinese group of gout were 49.6% and 4.7%, respectively." (PMID 38082308, 2023). "Moreover, the more pathogenic variants carrying ABCG2, the earlier the onset of HUA and gout." (PMID 35922835, 2022). "Therefore, ABCG2 dysfunction will increase the risk of HUA and gout." (PMID 35922835, 2022). "Recent GWAS identified genetic variants in urate transporters (ABCG2, SLC2A9, SLC22A11) and metabolic genes (GCKR, ADH1B) to be associated with the transition from hyperuricaemia to gout, and several of these associated with serum urate (SU) and gout in previous studies." (PMID 35633389, 2022). "Moreover, ABCG2 has an established key role in the onset and in severity of gout." (PMID 33926105, 2021). "Recent publications also suggest that ABCG2 is particularly involved in intestinal urate elimination and thus may represent an interesting new target for pharmacotherapeutic intervention in hyperuricemia and gout." (PMID 34206432, 2021). "ABCG2 SNPs rs2231142 (Q141K) and rs10011796 and, for comparison, the SLC2A9 SNP rs11942223 were tested for allelic association with (a) gout in the presence of HU (gout vs. HU), (b) gout per se (gout vs. all controls), (c) HU (HU vs. NU) and, (d) serum urate levels in controls." (PMID 32164793, 2020). "Of note, ABCG2 knockdown in endothelial cells induces increased secretion of the neutrophil chemoattractant IL-8, which might provide some mechanistic insights into gout pathophysiology." (PMID 32104502, 2020). "For ABCG2 polymorphisms, mainly studied in Asians, carrying 1–2 minor-allele-genotypes of rs2231142 and rs72552713 were respectively about 2.1–4.5 and 2.5–3.9 times higher odds of gout than non-minor-allele-genotypes." (PMID 33087043, 2020). "The percentage of males might be a potential source of heterogeneity in the effects of ABCG2 and SLC2A9 on gout, since the risk or protective effects were consistently stronger in men; this may indicate sex-specific differences in pathological mechanisms or in the handling of urate." (PMID 33087043, 2020). "ABCG2 rs2231142 may predict the risk of kidney comorbidities for Chinese Han male gout patients, but not allopurinol response." (PMID 31367212, 2019). "The results indicated that ABCG2 rs2231142 may predict the risk of specific kidney comorbidities for primary gout patients in a population of Chinese Han male, but not allopurinol response." (PMID 31367212, 2019). "Although 4-PBA and colchicine are relatively non-specific agents, these relatively non-toxic molecules may have clinical value in the treatment of gout, and in fact, colchicine may at least partially evoke its beneficial effect in gout by increasing ABCG2 expression." (PMID 29749379, 2018). "Interestingly enough, none of the novel ABCG2 mutant variants discovered in this work have been found in clinical samples of cancer-related conditions or the genetics of gout." (PMID 29061978, 2017). "In summary, the ABCG2 model and in silico simulations presented here may have significant impact on understanding drug distribution and toxicity, as well as drug development against cancer chemotherapy resistance or gout." (PMID 27741279, 2016). "However, the relationship between common defects in ABCG2 function and the risk of gout has not yet been fully characterized in Han Chinese patients." (PMID 24857923, 2014). "Data were analyzed based on the presence or absence of the ABCG2 141 K gout risk allele." (PMID 24476385, 2014).
gout (continued). "Our findings on gender-specific association between male but not female gout patients and rs2231142 in ABCG2 gene are likely to be true positive results but some other gender effects may have been overlooked." (PMID 19890391, 2009). "In recent years, both ABCG2 and SLC2A9 have been attempted to use as drug targets to treat hyperuricemia and gout." (PMID 41075270, 2025). "In hyperuricemia and gout patients, depletion of SCFA-producing bacteria leads to reduced ABCG2 and uricase expression in intestinal epithelial cells, impairing effective UA clearance." (PMID 41583434, 2025). "The genes ABCG2 and SLC2A9 were found to be the major genetic factors governing gout in Taiwan (Province of China)." (PMID 40535434, 2025). "In this study, we also investigated ABCG2 and SLC2A9 in participants with gout and asymptomatic hyperuricemia." (PMID 38397902, 2024). "The involved genes were ABCG2, SLC2A9, PKD2, ZNF518B, ALDH2, HECTD4, and MAPKAPK5 in the phenotype of gout; and only gene SLC2A9 was found in the AH phenotype." (PMID 36221101, 2022). "GWAS showed that the genetic variation of ABCG2 seems to be one of the reasons for the genetic heterogeneity of ROL and RUE gout." (PMID 35922835, 2022). "A transcript assay revealed that PDK2 and ABCG2 gene expression levels are positively correlated; thus, the regulators of PDK2 interact with ABCG2 to indirectly influence gout incidence." (PMID 35813212, 2022). "Our understanding of the genetic variations in the ABCG2 sequence associated with hyperuricemia and gout is still incomplete, as evidenced by the recent discovery of less common polymorphisms previously unrecognized or not studied in the context of hyperuricemia and gout." (PMID 34206432, 2021). "The effect size of ABCG2 rs2231142 on urate is ~ 60% that of SLC2A9, yet the effect size on gout is greater." (PMID 32164793, 2020). "Selection pressure analysis revealed significant enrichment of selection for the ABCG2 and ALDH2 loci in Japanese gout patients of each subtype." (PMID 32238385, 2020). "Three significant loci were found from normal type gout: rs548944057 of SLC28A3-NTRK2 (pmeta=2.91×10–8; OR=4.04), rs4148155 of ABCG2 (pmeta=3.64×10–8; OR=2.34) and rs146978188 of CD2-PTGFRN (pmeta=4.93×10–8; OR=6.31)." (PMID 32238385, 2020). "For example, urate transporter genes ABCG2, SLC2A9, and SLC22A12 modulate the relationship of renal urate homeostasis and gout with T2DM." (PMID 30615649, 2019). "ABCG2 and a novel gene, SLC17A4, contributed to the development of gout from hyperuricemia (OR = 1.56, PFDR = 3.68E-09; OR = 1.27, PFDR = 0.013, respectively)." (PMID 28252667, 2017). "Recent reports also show the significance of transporter genes such as ABCG2, NPT1/SLC17A1, MCT9/SLC16A9, and OAT4/SLC22A11, for the pathogenesis of gout." (PMID 24366390, 2014). "Another example was a missense coding variant in ABCG2 (rs35965584, MAFAFR=0.002, not present in AMR, EAS, EUR), for which our analysis identified a novel association with gout." (PMID 37425708, 2023). "Our data suggest that the leukocytes of gout patients respond differentially to hyperuricemia and its comorbidities and increase the gene expression of ABCG2 and IL-1β compared to normouricemic and non-gout controls." (PMID 35505381, 2022). "To enhance the prediction efficacy of genetic predictors, we selected two additional variations, rs2231142.GG of ABCG2 and rs11231463.GG of SLC22A9/OAT7, based on their contributions to gout in the development cohort and their effects on renal urate handling as reported." (PMID 35264217, 2022). "Interestingly, ABCG2, PKD2, and SPP1 genes were found to be significantly related to gout/AH in all three comparisons (gout vs normal; gout vs AH; AH vs normal)." (PMID 36221101, 2022).
gout (continued). "Through this strategy, our results suggested that epistatic interactions between PDK2 and ABCG2 contributed to serum urate and gout and that PKD2 is supposed to influence the progression from elevated serum urate to hyperuricemia to gout by epistatically interacting with ABCG2." (PMID 32000861, 2020). "Therefore, an updated systematic review and meta-analysis regarding the influence of SNPs in ABCG2 and SLC2A9 on gout, hyperuricemia and serum urate is needed." (PMID 33087043, 2020). "We supposed that PKD2 can indirectly influence the development of gout, by interacting with ABCG2 since no direct role of PKD2 have been identified until now." (PMID 32000861, 2020). "In addition, a recent GWAS found that ABCG2, SLC2A9, ALDH2, and novel loci induce asymptomatic hyperuricemia into gout development." (PMID 33087043, 2020). "In humans, some polymorphic variants of the transporter BCRP (also known as ATP-binding cassette transporter, sub-family G, member 2, ABCG2), which secretes UA into the intestine, result in decreased transporter activity, elevated serum uric acid (SUA) and increased incidence of gout." (PMID 30142173, 2018). "Despite the association of GCKR and ABCG2 with both gout and reduced coffee intake, our mediation analysis indicates that the dominant mechanism for GCKR and ABCG2 on gout risk is not through coffee consumption." (PMID 29976226, 2018). "Association of coffee consumption with gout was independent of all SNPs, and association of GCKR and ABCG2 SNPs with gout was independent of coffee consumption." (PMID 29976226, 2018). "Genome-wide significant associations with serum urate and gout were identified for known loci at SLC2A9 and ABCG2, but not for novel loci." (PMID 30181573, 2018). "In females, ABCG2 and TRIM46 contributed to the risk of gout (both P < 0.05), but neither was significant after multiple correction (both PFDR > 0.05)." (PMID 28252667, 2017). "Taken together, these findings suggest that among genes in a gout-susceptibility locus, not ALPK1 but ABCG2 is important as a susceptible gene for gout." (PMID 25326865, 2015). "Genetic variations in the ABCG2 gene have been reported to influence serum uric acid levels and to participate in the pathogenesis of gout, but no further data have been reported in the Han Chinese population." (PMID 24857923, 2014). "Furthermore, the ABCG2 gene played a crucial role in the aberrant generation of pro-inflammatory cytokines such as interleukin-1 beta (IL-1β), tumor necrosis factor-alpha (TNF-α) and IL-8 in gout." (PMID 36967798, 2023). "However, the BAZ1B variation has a significant correlation with gout with or without ABCG2 dysfunctional variation." (PMID 35922835, 2022). "Low-level or non-functional ABCG2 expression may increase individual drug toxicity, reduce cancer drug resistance, and result in hyperuricemia and gout." (PMID 31254042, 2020). "There have been 12 studies of ABCG2-rs2231142 on gout published after these reviews and most reviews did not pool genotype effects, which could lead to suggest mode of gene effects." (PMID 33087043, 2020). "Some variation in gout prevalence may be specifically attributable to genetic factors, such as variation in renal urate transporter genes, particularly SLC2A9 and ABCG2." (PMID 29996922, 2018). "Because ABCG2, a major causative gene for gout, also locates in the gout-susceptibility locus on chromosome 4q, these findings suggest that among genes in a gout-susceptibility locus, not ALPK1 but ABCG2 could be important as a gout-susceptible gene." (PMID 25326865, 2015). "This hypothesis is further supported by the observation that the effect size of ABCG2 on urate in Europeans and Japanese is 58% and 73% that of SLC2A9, the most influential urate locus, respectively, yet the effect size of ABCG2 on gout is consistently larger than that of SLC2A9." (PMID 32164793, 2020).